FGF23 (fibroblast growth factor 23)
Diseases named in the same sentence as FGF23 in open-access papers (continued):
Sharing a sentence is not in itself a finding about the gene and the disease.
hypophosphatemia (continued). "According to a study testing FCM infusions in women ofsimilar age to our patient, the rise in ferritin level post FCM correlated with rises in serumFGF23 level and declines in serum phosphate levels, suggesting that greater rises in ferritinincrease risk of FGF23-induced hypophosphatemia." (PMID 38746049, 2024). "According to research, FCM causes an acute increase in blood levels of physiologically active fibroblast growth factor 23, which in turn causes a rise in urine phosphate excretion and a decrease in serum levels of 1,25-dihydroxyvitamin D, leading to a high prevalence of hypophosphatemia." (PMID 39835061, 2024). "Hypophosphatemia associated with intact FGF23 concentration greater than 40 pg/ml may be a crucial marker for the early diagnosis of XLH in pediatric patients." (PMID 38706696, 2024). "In this disorder, hypophosphatemia has been linked with iron depletion and elevated FGF23." (PMID 37375595, 2023). "Although an increased level of serum FGF-23 concentrations cannot cause hypophosphatemia in patients undergoing dialysis, it is unknown if FGF-23 buildup can directly influence bone mineralization." (PMID 36812096, 2023). "A Japanese study of OPLL patients reported that increased plasma FGF23 and lower plasma phosphate are associated with more rapidly progressing OPLL, additionally supporting FGF23 associated hypophosphatemia as a pathogenic mechanism for spinal enthesopathy [110, 111••]." (PMID 37530996, 2023). "In the present study, we used dietary Pi supplementation and the osteocyte-specific deletion of Fgf23 to correct hypophosphatemia in order to study the respective contributions of FGF23 excess, hypophosphatemia, and DMP1 deficiency to the bone defects in adult Dmp1-null mice." (PMID 37943605, 2023). "Given that elevated FGF23 in XLH is the cause of hypophosphatemia, with the latter being a major driver of osteomalacia and fractures in adults, neutralization of FGF23 with burosumab, and restoring serum phosphate levels, was anticipated to potentially reduce the risk of future fractures." (PMID 37547321, 2023). "Thus, a high level of FGF23 causes renal phosphate wasting, hypophosphatemia, and decreased serum active vitamin D. Chronic hypophosphatemia ultimately results in osteomalacia." (PMID 37554164, 2023). "It is hypothesized that hypophosphatemia and osteomalacia associated with increased FGF23 in XLH can lead to temporal bone malformation." (PMID 37547321, 2023). "Furthermore, conventional treatment increases FGF23 levels and thus can aggravate hypophosphatemia and calcitriol deficiency." (PMID 37048797, 2023). "Therefore, ARHR1 is second monogenic disorder in patients with inherited FGF23-related hypophosphatemia that is associated with spinal ligament ossifications." (PMID 37530996, 2023). "The excess and deficiency of FGF23 lead to hypophosphatemia and hyperphosphatemia, respectively." (PMID 35654784, 2022). "Increased renal tubular loss of phosphorus is a cause of hypophosphatemia; it could be due to a tumor producing FGF-23 or a genetic disorder (XLH) caused by an inactivating mutation in the PHEX gene." (PMID 36382755, 2022). "However, several studies suggest that tumor-induced osteomalacia is the most common acquired cause of FGF23-induced hypophosphatemia, has a medium onset age of 40–45 years, and affects both genders equally." (PMID 35381903, 2022). "Pharmacological management includes vitamin D repletion (according to specific guidelines), phosphate supplementation, use of active vitamin D analogue if FGF-23 mediated hypophosphatemia is present, and treatment of associated hyperfunctioning endocrinopathies accordingly." (PMID 35420267, 2022). "In the kidney, increasing FGF23 levels causes hypophosphatemia and decreased calcitriol levels." (PMID 35269640, 2022).
hypophosphatemia (continued). "Therefore, high FGF23 levels are associated with worse hypophosphatemia, which then leads to severe defects of bone mineralization in FGF23-mediated hypophosphatemic rickets/osteomalacia." (PMID 35769089, 2022). "Preoperative FGF-23 levels are associated with post-transplant hypophosphatemia." (PMID 35602513, 2022). "Due to this, it appears that DMP1 could negatively regulate FGF23 during bone development and that secondary hypophosphatemia in FGF23 elevation could be the cause of rickets, but osteomalacia depends on other DMP1 functions." (PMID 34360805, 2021). "Elevated levels of FGF23 were reported mainly in genetic X-linked hypophosphatemia (XLH) and non-genetic tumor-induced osteomalacia (TIO), a rare condition of hypophosphatemia caused due to increased levels of FGF23 and associated with low levels of 1,25-(OH)2D." (PMID 34572066, 2021). "The major cause of acquired FGF23-related hypophosphatemia is TIO." (PMID 34901334, 2021). "However, in rare cases, the intravenous administration of saccharated ferric oxide, ferric polymaltose and carboxymaltose was reported from our laboratory and others to cause FGF23-related hypophosphatemia." (PMID 34901334, 2021). "It is associated with hypophosphatemia, elevated FGF23 and abnormal levels of 1,25(OH)2D3." (PMID 34360805, 2021). "Maternal iron deficiency is associated with perturbed expression and/or regulation of FGF23 and hence might be implicated in the pathogenesis of hypophosphatemia-driven rickets in their offspring." (PMID 33675347, 2021). "Therefore, he was referred to our division and admitted to examine the cause of FGF23-related hypophosphatemia." (PMID 34901334, 2021). "Importantly, elevated serum FGF-23 levels, accompanied with hypophosphatemia, were associated with different syndromes in mice and humans, which is far beyond the aim of this review." (PMID 33396566, 2020). "Other rare genetic diseases involving osteoglophonic dysplasia, McCune–Albright syndrome, Raine syndrome, opsismodysplasia, etc., could also cause hypophosphatemia through influencing FGF23 concentration." (PMID 33015068, 2020). "The lack of either skeletal abnormality or genetic mutation in these patients indicates that FGF23 may contribute to the development of these manifestations either directly or via hypophosphatemia." (PMID 30808384, 2019). "Additionally, treatment with an adeno-associated virus that produced Klotho resulted in increased circulating serum Klotho and caused FGF23-related hypophosphatemia in mice." (PMID 30627598, 2019). "Indeed, most manifestations of XLH are now known to be caused by FGF23-induced hypophosphatemia resulting from downregulation of sodium-phosphate transporters in the renal distal tubule, and repression of serum calcitriol." (PMID 30808384, 2019). "However, a human disease called osteoglophonic dysplasia caused by activating mutations in FGFR1 is often associated with hypophosphatemia due to increased FGF23 levels, which also suggests the regulation of FGF23 production by FGFR signaling." (PMID 30972027, 2019). "Indeed, most inherited forms of hypophosphatemia are caused by mutations that directly increase serum concentrations of FGF23 and/or the activity of its receptors." (PMID 30808384, 2019). "In addition to diseases with known genetic causes, hypophosphatemia with high FGF23 has been reported in patients receiving some intravenous iron preparations." (PMID 29515522, 2018). "Thus, FGF23 antagonists can be used to reduce inherited and tumor-induced hypophosphatemia, and organ transplantation and intravenous iron treatment-caused hypophosphatemia." (PMID 29949887, 2018). "In contrast, FGF23 levels are low in patients with chronic hypophosphatemia from other causes such as vitamin D deficiency and Fanconi syndrome indicating that circulatory FGF23 level is suppressed in these patients by hypophosphatemia or other accompanying metabolic changes." (PMID 29515522, 2018).
hypophosphatemia (continued). "Firstly, extraskeletal overexpression of FGF23 also causes hypophosphatemia and osteomalacia." (PMID 27035636, 2016). "FGF23 inhibits the sodium-phosphate cotransporters 2a and 2c and thus augments urinary phosphate excretion; an excessive loss of phosphate in the urine results in hypophosphatemia." (PMID 26491212, 2015). "Thus, our studies demonstrated that activation of the ERK1/2 signaling pathway by FGF23 is critical to the pathogenesis of hypophosphatemia and 1,25(OH)2D deficiency in Hyp mice." (PMID 26588476, 2015). "Further studies are needed to assess possible effects of cinacalcet on plasma phosphate and FGF-23, including whether an effect may vary according to the etiology of hypophosphatemia and between different genetic mutations in patients with HR." (PMID 24660072, 2014). "Tumor-induced osteomalacia (TIO) is a rare condition associated with hypophosphatemia, myopathy, and systemic bone demineralization caused by renal phosphate wasting in conditions of excessive production of fibroblast growth factor 23 (FGF23) by neoplasmatic, most often, benign lesions." (PMID 24639905, 2014). "Originally, FGF23 was identified by positional cloning of the gene responsible for autosomal dominant hypophosphatemic rickets, a condition in which elevated serum levels of active FGF23 cause hypophosphatemia with resultant rickets/osteomalacia." (PMID 24678415, 2014). "While hypophosphatemia in the Fam20c conditional knockout mice can be attributed to the overproduction of FGF23 in the abnormal skeleton, the direct cause of cell differentiation failure may be complicated." (PMID 22615579, 2012). "We hypothesized that FGF23 may be a crucial factor because previous studies show that FGF23 is a causative factor of hypophosphatemia and osteomalacia and forced FGF23 expression in osteoblasts inhibits mineralization and promotes osteomalacia." (PMID 22629419, 2012). "The Dmp1 KO phenotype is associated with hypophosphatemia and elevated FGF-23 concentrations." (PMID 21542006, 2011). "Furthermore, not all genetic causes may be found by sequencing of exons and exon-intron junctions of known pathogenic genes for FGF23-mediated hypophosphatemia." (PMID 41445556, 2025). "Laboratory tests revealed hypophosphatemia (0.32 mmol/L), elevated alkaline phosphatase (429 U/L, normal range: 45 to 125 U/L), 25 (OH) D deficiency (16.25 ng/mL, normal range: >30), and an elevated level of FGF23 (158.7 pg/mL, normal range: 23.3 to 95.4 pg/mL)." (PMID 39993076, 2025). "There remain unknown PV and CNV, which can cause FGF23-mediated hypophosphatemia." (PMID 41445556, 2025). "Therefore, it is possible that acute hepatitis also increases FGF23 production by the osteocytes, which could significantly contribute to the circulating levels measured in our patients and cause their hypophosphatemia." (PMID 39525686, 2024). "FGF23 also suppresses 1-α-hydroxylase, intensifying the unavailability of biologically active vitamin D. So, the net effect of hypovitaminosis D or dietary deficiency of calcium is hypocalcemia, hypophosphatemia, decreased osteoblastic activity, and increased levels of PTH." (PMID 39301310, 2024). "Moreover, we used two mouse models of hypophosphatemia—induced either by dietary intervention in the form of a low phosphorus (LP) diet (0.02% of Pi) or genetically in a mouse model of X-linked hypophosphatemia (XLH)–that had opposite FGF23 levels." (PMID 39666728, 2024). "Although some observations suggest that hypophosphatemia may be associated with a favorable prognosis in terms of liver function recovery, its importance, link with ectopic production of FGF23, and exact role as a biomarker or therapeutic target require further clarification." (PMID 39525686, 2024). "In addition to clinical signs, hypophosphatemia associated with intact FGF23 plasma concentration greater than 40 pg/mL, assessed by the Liaison® XL assay, may be a crucial marker for the early diagnosis of XLH in pediatric patients." (PMID 37991698, 2024).
hypophosphatemia (continued). "This case raises two questions: (i) Can elevated cFGF23 cause mild hypophosphatemia in the setting of iron deficiency; (ii) Is the use of cFGF23 assays to differentiate between the causes of hypophosphatemia appropriate in the setting of serum FGF23 disturbances such as iron deficiency." (PMID 37808399, 2023). "Currently, the mechanism of preparation-specific risks for hypophosphatemia is not fully understood, but the carbohydrate backbones of certain iron formulations, including FCM, may inhibit the cleavage of intact FGF23, leading to renal phosphate loss and hypophosphatemia." (PMID 35790696, 2022). "Furthermore, we emphasize diagnostic pitfalls when dealing with FGF-23-induced hypophosphatemia." (PMID 31963334, 2020). "After transplant, recovery of bone health may be impaired by nutritional vitamin D deficiency, persistent hyperparathyroidism, tertiary FGF-23 excess, hypophosphatemia, immunosuppressive therapy with corticosteroids and/or calcineurin inhibitors (CNI), and alteration of sex hormones." (PMID 24605319, 2014). "Subsequent workup by the endocrinologist was notable for elevated FGF-23 activity (257 RU/mL), hypophosphatemia (1.1 mg/Dl), hypophosphaturia, low 1,25-dihydroxy vitamin D (13 pg/mL), and low 24-hour urinary calcium levels." (PMID 41438661, 2026). "As in other FGF23-mediated hypophosphatemia conditions, individuals with CSHS have renal phosphate wasting and inappropriately normal or frankly low 1,25-dihydroxyvitamin D levels with resultant hypophosphatemia leading to rickets and osteomalacia." (PMID 41907689, 2026). "Pediatric cases of XLH typically present with elevated levels of serum fibroblast growth factor 23 (FGF23), hypophosphatemia, rickets, and impaired growth." (PMID 42079344, 2026). "Tumor-induced osteomalacia (TIO) is an ultra-rare paraneoplastic syndrome caused by excessive secretion of fibroblast growth factor 23 (FGF23) from phosphaturic mesenchymal tumors, leading to renal phosphate wasting, hypophosphatemia, and osteomalacia." (PMID 41737823, 2026). "We describe a 46-year-old woman with MAS and extensive FD who presented with worsening bone pain and FGF-23-mediated hypophosphatemia." (PMID 42100588, 2026). "BACKGROUND: X-linked hypophosphatemic rickets (XLH) is a rare inherited metabolic bone disorder caused by excess fibroblast growth factor 23 (FGF23), leading to hypophosphatemia and rickets." (PMID 41501877, 2026). "Burosumab, a monoclonal antibody against FGF-23, is approved for X-linked hypophosphatemia and tumor-induced osteomalacia and has shown promise in case reports of pediatric and adult patients with MAS-related FGF-23-mediated hypophosphatemia." (PMID 42100588, 2026). "This case represents the second reported adult and oldest patient treated with burosumab for MAS-related FGF-23-mediated hypophosphatemia after failure of conventional therapy." (PMID 42100588, 2026). "Excessive FGF23 leads to increased urinary phosphate excretion and decreased serum phosphate levels, resulting in hypophosphatemia and osteomalacia." (PMID 41438661, 2026). "In our patient, the high fractional excretion of phosphate (20.4%) and inappropriate renal phosphate wasting (740 mg/24hr) in the setting of severe hypophosphatemia is consistent with the renal phosphate wasting effect of FGF23." (PMID 40922882, 2025). "We present a narrative review of FGF23-mediated hypophosphatemic osteomalacia and propose a roadmap for investigating the etiology of hypophosphatemia to guide therapy." (PMID 41445556, 2025). "Hypophosphatemia due to FGF23 hypersecretion is generally more severe than in hyperparathyroidism due to lower 1,25(OH)2VitD levels." (PMID 40297189, 2025). "Like other disorders of FGF23 excess, management of hypophosphatemia in FD has traditionally focused on repletion with oral phosphate and active vitamin D analogs." (PMID 41480037, 2025).
hypophosphatemia (continued). "The molecular effect resembles XLH—the lack of active PHEX protein leads to the overexpression of the FGF23 gene, resulting in hyperphosphaturia and hypophosphatemia." (PMID 41008628, 2025). "Among the forms of FGF23-dependent hypophosphatemia with a genetic etiology, the most common is certainly X-linked hypophosphatemia (XLH), which can be considered the prototype of a hereditary disorder caused by loss of phosphate at the renal level." (PMID 39377903, 2025). "We propose an approach for investigating the etiology of hypophosphatemia along with an illustrative case of a 29-yr-old female with PHEX PV-negative FGF23-mediated hypophosphatemic osteomalacia responding well to burosumab." (PMID 41445556, 2025). "The consequences of FGF23 excess are renal phosphate wasting and decreased calcitriol synthesis, leading to hypophosphatemia and subsequently rickets and osteomalacia." (PMID 40295317, 2025). "Biochemical analysis reveals a pattern of disturbances similar to XLH with dominating hypophosphatemia, hyperphosphaturia, low concentration of 1,25(OH)2D, and elevated or “inadequately” normal concentration of FGF23." (PMID 41008628, 2025). "Serum intact FGF23 levels are likely elevated or inappropriately normal in the setting of hypophosphatemia." (PMID 41445557, 2025). "Oral phosphate and calcitriol were the mainstay of medical therapy, however, the development of burosumab, a monoclonal blocking antibody to FGF23, has introduced an approved therapy that improves hypophosphatemia and symptoms in patients with TIO." (PMID 39755803, 2025). "This process has been described as the 6H-syndrome—Hypophosphatemia and Hyperphosphaturia, driven by High FGF-23 with secondary effects of Hypovitaminosis D, Hypocalcemia, and secondary Hyperparathyroidism." (PMID 41445550, 2025). "High serum FGF23, low serum 1,25(OH)2VitD, and adequate serum 25(OH)VitD should raise the suspicion of FGF23-mediated hypophosphatemia." (PMID 40297189, 2025). "This rare condition was recently reported in 2 alcoholic patients, with marked improvement upon cessation of alcohol consumption, suggesting a link between alcohol and FGF23-related hypophosphatemia within the highly limited cases." (PMID 39963340, 2025). "This leads to increased fibroblast growth factor 23 synthesis, prompting renal phosphate wasting and hypophosphatemia." (PMID 41467153, 2025). "The term “6H syndrome” has been coined to explain the constellation of biochemical changes seen after i.v. iron infusion: high FGF23, hyperphosphaturia, hypophosphatemia, hypovitaminosis D, hypocalcemia, and secondary hyperparathyroidism." (PMID 41445551, 2025). "In January 2025, a fascinating study was published, analyzing 13 adults with FGF23-dependent hypophosphatemia." (PMID 41008628, 2025). "Alcoholic osteomalacia is a recently suggested entity of the acquired form of FGF23-related hypophosphatemia, and the current patient is the third reported case of such a scenario." (PMID 39963340, 2025). "Among them, only one had hypophosphatemia and the other serum phosphorus levels at the lower limit, both with FGF23, αKlotho, 25OHD3 and PTH within the reference range." (PMID 40133996, 2025). "FGF23-mediated hypophosphatemia has high or inappropriately normal FGF23 levels and usually presents with low or normal 1,25(OH)2D319 and normocalcemia." (PMID 41445556, 2025). "In those with a renal cause, the next important step is to identify if it is FGF23-mediated or FGF23-independent, as FGF23-mediated hypophosphatemia can be managed with burosumab." (PMID 41445556, 2025). "Investigations showed partial Fanconi syndrome; nevertheless, he had profound hypophosphatemia, low 1,25-OH vitamin D and raised FGF23 levels suggesting a diagnosis of tumor-induced osteomalacia." (PMID 39888445, 2025). "As expected, Hyp mice showed significantly elevated FGF23 levels and a concomitant hypophosphatemia compared to wildtype (WT) littermates." (PMID 41384828, 2025).